EDA (ectodysplasin A)
Diseases named in the same sentence as EDA in open-access papers (continued):
Sharing a sentence is not in itself a finding about the gene and the disease.
tooth agenesis (continued). "Several genes, including MSX1, PAX9, AXIN2, WNT10A and EDA have been reported to involve in tooth agenesis." (PMID 33014315, 2020). "Most often reported genes associated with nonsyndromic tooth agenesis are PAX9, MSX1, EDA, and AXIN2." (PMID 31781599, 2019). "Most often reported genes associated with the familial form of the nonsyndromic tooth agenesis are paired box gene 9 (PAX9), Msh homeobox 1 (MSX1), ectodysplasin A (EDA), and axis inhibitor protein 2 (AXIN2)." (PMID 31781599, 2019). "The proband was screened for mutations of genes previously related to tooth agenesis (i.e., PAX9, AXIN2, EDA, WNT10A, etc.)by targeted exome sequencing (TES), with next generation technology." (PMID 27917906, 2016). "PAX9, MSX1, AXIN2, WNT10A and EDA have been experimentally established for congenitally missing teeth like hypodontia and oligodontia." (PMID 25203534, 2014). "In conclusion, this is the first study to report two simultaneous gene mutations of EDA and WNT10A in HED and isolated tooth agenesis patients." (PMID 24312213, 2013). "The other four EDA mutations identified in HED patients and the two WNT10A mutations have been reported in tooth agenesis patients previously." (PMID 24312213, 2013). "In this study, we investigated the contribution of WNT10A, EDA, EDAR and EDARADD mutations in patients with isolated or syndromic tooth agenesis." (PMID 24312213, 2013). "Digenic mutations of both EDA and WNT10A were identified in 2 of 88 (2.27%) isolated oligodontia cases and 4 of 26 (15.38%) syndromic tooth agenesis cases." (PMID 24312213, 2013). "At present, mutations causing non-syndromic tooth agenesis have been identified in MSX1, PAX9, AXIN2, EDA, and WNT10A." (PMID 23227268, 2012). "Both carrier parents of ED28 had mild hypodontia, suggesting that carriers of only one affected EDAR allele may show mild phenotype, similar to female carriers of XL EDA mutations." (PMID 34573371, 2021). "In mouse and dog models of congenital tooth agenesis associated with ectodysplasin A (EDA) 1 deficiency, administering an agonist antibody targeting EDA1 or recombinant EDA1 protein rescued the number, position, shape, and timing of the eruption of missing teeth." (PMID 34211084, 2021). "In our studies, we found that a known EDA mutation c.1013C>T (p.T338M) was associated with nonsyndromic tooth agenesis, and the mutation was located in the TNF homology domain, which was first reported in 2008." (PMID 34545288, 2021). "When considering isolated cases or the nonsyndromic form, many studies have investigated the correlation between tooth agenesis and genetic mutations present in individuals belonging to one and the same family, attributing the mutations to genes PAX9, MSX1, AXIN2, and EDA." (PMID 25215247, 2014). "Candidate genes, such as PAX9, MSX1, AXIN2, and EDA, are related to etiology of tooth agenesis." (PMID 25215247, 2014). "In this study, digenic mutations of both WNT10A and EDA caused isolated and syndromic tooth agenesis, and the protein structure analyses indicated that all the WNT10A and EDA mutations may affect protein function." (PMID 24312213, 2013). "MSX1, PAX9, AXIN2, WNT10A, and EDA are proven candidate genes for familial tooth agenesis." (PMID 23227268, 2012). "We cannot exclude a potential role of EDA variant in the etiopathogenesis of hypodontia in our patient, but without a positive family history and with his mother being healthy, it appears more likely that the dental anomalies, along with other symptoms, were caused by LTBP3 variant." (PMID 34573388, 2021). "To date, mutations in AXIN2 (axis inhibition protein 2), EDA (ectodysplasin A), MSX1 (msh homeobox 1), PAX9 (paired box 9) and WNT10A (wingless-type MMTV integration site family, member 10a) have been demonstrated to be associated with non-syndromic tooth agenesis." (PMID 24278334, 2013).
tooth agenesis (continued). "The genetic basis of tooth agenesis is well-established, with several genes identified as controlling factors, namely MSX1, PAX9, AXIN2, EDA, IRF6, FGFR1, and WNT10A." (PMID 40040530, 2025). "Of these, EDA, EDAR, EDARADD, and WNT10A are candidate genes of both non‐syndromic tooth agenesis and syndromic tooth agenesis (STA)." (PMID 33943035, 2021). "WNT10A, EDA, EDAR and EDARADD were sequenced in 88 patients with isolated oligodontia and 26 patients with syndromic tooth agenesis." (PMID 24312213, 2013).
X-linked hypohidrotic ectodermal dysplasia (30 papers, 2008 to 2025). An X-linked form of ectodermal dysplasia which results from mutations of the gene encoding ectodysplasin. "Tabby is an animal model for the human ectodermal disorder XLHED (X-linked hypohidrotic ectodermal dysplasia), which is also caused by mutation of the EDA gene, and patients affected by XLHED have been demonstrated to have reduced salivary output." (PMID 25409170, 2014). "Mutations in EDA gene can lead to X-linked hypohidrotic ectodermal dysplasia (XLHED), the most common form of ectodermal dysplasias (EDs)." (PMID 23626789, 2013). "X-linked anhidrotic ectodermal dysplasia is a disorder characterized by abnormal development of tissues and organs of ectodermal origin caused by mutations in the EDA gene." (PMID 21740563, 2011). "The EDA gene mutation can lead to X-linked hypohidrotic ectodermal dysplasia (XLHED) and non-syndromic tooth agenesis (NSTA)." (PMID 39048976, 2024). "Classically, EDA gene defects are thought to be associated with the occurrence of X-linked hypohidrotic ectodermal dysplasia (XLHED)." (PMID 37091044, 2023). "Ectodysplasin A (Eda) gene plays a role in ectodermal-mesenchymal interactions and mutation leads to a genetic syndrome X-linked hypohidrotic ectodermal dysplasia (XLHED) in humans." (PMID 34222243, 2021). "Among these, EDA mutations could cause SH, which appears as an X-linked hypohidrotic ectodermal dysplasia (XLHED) clinical feature, and they have also been linked to isolated tooth agenesis, most likely due to complete or partial disruption of the EDA signalling pathway." (PMID 34545288, 2021). "One of the most striking examples is the use of a prenatal protein replacement strategy for the treatment of X-linked hypohidrotic ectodermal dysplasia (XLHED), an ectodermal dysplasia caused by loss-of-function mutations in the EDA gene." (PMID 34422015, 2021).
Oligodontia (18 papers, 2009 to 2024). The absence of six or more teeth from the normal series by a failure to develop. "This study successfully identified two EDA missense mutations associated with oligodontia exhibiting variable expression of ED, one of which is novel." (PMID 39858559, 2024). "Mice with knockouts of MSX1, PAX9, and EDA, which are the causative genes of oligodontia in humans, demonstrate developmental arrest of tooth formation or a decrease in tooth number." (PMID 36833267, 2023). "Our results suggest that WNT10A and EDA digenic mutations could result in oligodontia and syndromic tooth agenesis in the Chinese population." (PMID 24312213, 2013). "HED is the most frequently mentioned syndrome with oligodontia, while EDA and WNT10A mutations constitute the most frequently determined genetic cause: 30.4% of the syndromic oligodontia." (PMID 38132417, 2023). "Mutations in numerous genes including msh homeobox 1 (MSX1), paired box 9 (PAX9), Wnt family member 10A (WNT10A), axis inhibition protein 2 (AXIN2), ectodysplasin A (EDA), and Wnt family member 10B (WNT10B) have been associated with nonsyndromic oligodontia." (PMID 30134957, 2018). "For example, mutations in the EDA gene are the cause of some XLHED and non-syndromic oligodontia in patients, and the two diseases are considered to be the same disease with different degrees of severity." (PMID 27657131, 2016). "Numerous studies have shown that mutations in the EDA gene can cause X-linked ectodermal dysplasia (ED) and non-syndromic oligodontia (NSO)." (PMID 39858559, 2024). "Inactivation mutation of the EDA gene or the genes coding for its receptors can result in hypohidrosis ectodermal dysplasia (HED), a condition that is characterized by oligotrichosis, edentulosis or oligodontia, and oligohidrosis or anhidrosis." (PMID 34938205, 2021). "Genetic alterations in EDA and WNT10A cause particularly non-syndromic/isolated oligodontia." (PMID 31652981, 2019). "Microdontia of canines, dysmorphic cone-shaped incisors (d) and canines (c and d) and molar root fusion and shape anomalies (a and b) are associated with the phenotype of oligodontia and also linked to the ED1 mutation and molecular alterations of the EDA-NF-kappaB signalling pathway." (PMID 18760768, 2009). "In the present study, we investigated six genes (MSX1, PAX9, AXIN2, WNT10A, EDA and EDARADD) in a patient with sporadic non-syndromic oligodontia." (PMID 26406231, 2015). "We found a missense variant in AXIN2, but detected no pathogenic variants in MSX1, PAX9, EDA, EDAR, or EDARADD, genes that previously have been found in nonsyndromic oligodontia." (PMID 32234057, 2020).
hypohidrosis (7 papers, 2020 to 2025). diminished sweating in response to appropriate stimuli. "Genotype–phenotype correlation analysis revealed that patients with EDA missense mutations had a higher frequency of hypohidrosis (P = 0.021)." (PMID 32117440, 2020). "Genotype–phenotype analysis showed that compared with EDA deletion mutations, patients with EDA missense mutations had a higher frequency of hypohidrosis (P = 0.021)." (PMID 32117440, 2020).
Obesity (6 papers, 2018 to 2023). Accumulation of substantial excess body fat. "In summary, EDA, a hepatokine, may be associated with a variety of diseases, such as metabolic disorders, DN, and cancer, and may be a link among insulin resistance, T2DM, obesity, and NAFLD." (PMID 34938205, 2021). "Ectodysplasin A (EDA), a newly discovered hepatokine, is closely related to chronic diseases such as fatty liver, obesity, and insulin resistance." (PMID 34858327, 2021). "Furthermore, hepatic ectodysplasin A (EDA), together with its intronic miRNA, miR-676, was upregulated and released from hepatocytes under conditions of obesity and could act on SM as its main target tissue; its increased expression in liver occurs due to a systemic IR." (PMID 30648107, 2018).
Insulin resistance (4 papers, 2021 to 2023). Increased resistance towards insulin, that is, diminished effectiveness of insulin in reducing blood glucose levels. "Ectodysplasin A (EDA) was recently identified as a liver-secreted protein that is increased in the liver and plasma of obese mice and causes skeletal muscle insulin resistance." (PMID 33746906, 2021). "Ectodysplasin A (EDA), a member of the TNF family, plays important roles in ectodermal development, while recent studies expanded its regulatory effects on insulin resistance and lipid metabolism." (PMID 37091044, 2023).
anhidrosis (3 papers, 2021 to 2023). Lack of sweating or the ability to sweat when provoked by the appropriate stimulus. "Most patients with XLHED are hemizygous for EDA null mutations leading to the absence or inactivity of EDA1 and, with complete penetrance, to the full-blown phenotype of the disease characterised by anhidrosis." (PMID 36672894, 2023).
anodontia (3 papers, 2016 to 2023). Anodontia is an extreme developmental dental anomaly characterized by the complete absence of all teeth. "Mutations within the ectodysplasin A (EDA) gene have been associated with congenital hypotrichosis and anodontia (HAD/XHED) in humans, mice, dogs and cattle." (PMID 38275590, 2023). "Mutations in the EDA gene can not only lead to congenital anodontia syndrome, but also provoke congenital anodontia with relatively mild symptoms, which are not complicated with the developmental defects of ectoderm-derived tissues and organs." (PMID 30526585, 2018). "The genetic defects of EDA gene could lead to the incidence of asymptomatic congenital anodontia." (PMID 30526585, 2018). "We scanned another female with non-syndromic anodontia and her younger brother with the same gene mutations of the PAX9,MSX1,AXIN2 and EDA, but without developmental abnormalities in the dentition." (PMID 26759063, 2016).
breast carcinoma (3 papers, 2014 to 2022). "Together, this work identifies a novel death receptor oncogene in breast cancer, whose mechanism of transformation is based on the interaction between the WNT and Ectodysplasin A (EDA) pathways." (PMID 34916592, 2022).
colorectal cancer (2 papers, 2022). A primary or metastatic malignant neoplasm that affects the colon or rectum. "EDA, a type II transmembrane protein whose receptor acts as a component of the Wnt/β-catenin signaling pathway, can affect the occurrence of colorectal cancer." (PMID 35392242, 2022).
Anhidrotic ectodermal dysplasia (1 paper, 2010). "Mutations in the soluble form of the EDA protein and the EDA receptor are the cause of anhidrotic ectodermal dysplasia, a syndrome that results from impaired development of skin appendages during embryogenesis." (PMID 20167115, 2010).
craniofrontonasal syndrome (1 paper, 2017). "Furthermore, a contiguous deletion of a region containing EFNB1, ‘Oligophrenin 1’ (OPHN1), PJA1 and EDA was reported in patients with craniofrontonasal syndrome." (PMID 28877219, 2017).
dysplasia (1 paper, 2019). A usually neoplastic transformation of the cell, associated with altered architectural tissue patterns. "Hypohidrotic ectodermal dysplasia genes, including EDA, EDAR and EDARADD, were analyzed using next-generation sequencing (NGS)." (PMID 31452656, 2019).
incontinentia pigmenti (1 paper, 2024). Incontinentia pigmenti (IP) is a rare X-linked dominant multi-systemic ectodermal dysplasia usually lethal in males and presenting neonatally in females with a bullous rash along Blashko's lines (BL) followed by verrucous plaques evolving over time to hyperpigmented swirling patterns. "Incontinentia pigmenti (IP) (OMIM #308300), also known as Bloch-Sulzberger syndrome, is a rare genetic multisystem disorder grouped within the ectodysplasin A (EDA) pathway of ectodermal dysplasias." (PMID 39623400, 2024).
odonto-onychodermal dysplasia (1 paper, 2023). "Seven studies reported mutations in EDA or WNT10A in HED, Christ–Siemens–Touraine syndrome, tricho-odonto-onychodermal dysplasia, and odonto-onychodermal dysplasia." (PMID 38132417, 2023).
pemphigus (1 paper, 2021). Pemphigus is a group of rare autoimmune diseases that cause blistering of the skin and mucous membranes (mouth, nose, throat, eyes, and genitals).This conditioncan occur at any age, but often strikes people in middle or older age. "Several other skin homeostatic genes, including WIF1, EDA, RXRG, and TGFB2, were significantly decreased in pemphigus cases." (PMID 34660634, 2021).
periodontitis (1 paper, 2023). An acute or chronic inflammatory process that affects the tissues that surround and support the teeth. "In the Pg sample, we observed interactions between ADM and CALCRL, which is related to periodontitis; EDA and EDA2R, which is related to ectodermal development; and SPP1 and CD44 and SPP1 and (ITGA4+ITGB1), which promotes phosphoprotein secretion and regulates bone salinization." (PMID 37287452, 2023).
prediabetes (1 paper, 2021). "In a subset of the AIR registry, serum levels of ectodysplasin A2 (EDA-A2) also were associated with HbA1c and prediabetes (p < 0.05)." (PMID 34618839, 2021).
tumor (22 papers, 1995 to 2026). "EDA-FN is an alternatively spliced isoform of fibronectin that is selectively expressed in cancer-associated fibroblasts and tumor stroma, where it promotes extracellular matrix remodeling, tumor invasion, and immune evasion." (PMID 41590379, 2026). "In addition, EDA and its receptors have been implicated in tumor pathogenesis through the regulation of tumor cell proliferation, apoptosis, differentiation, and migration." (PMID 34938205, 2021). "Taken together, EDA knockout with CRISPR/Cas system provide a strategy for interrupting the interaction of tumor cells with their microenvironment, instead of eradicating cancer cells themselves." (PMID 29285230, 2017). "Therefore, we hypothesised that CD27, EDA, TNF, TNFRSF12A, TNFRSF13C, and TNFRSF9 may affect tumour prognosis mainly by regulating the TGF-β signaling pathway." (PMID 35392242, 2022). "In other words, CD27, EDA, TNF, TNFRSF12A, TNFRSF13C, and TNFRSF9 expression may also affect the immunotherapy effect on tumours by regulating the expression of immune checkpoint molecules in the tumour microenvironment." (PMID 35392242, 2022). "Moreover, within each RCC case, uPARAP and EDA expressions were not significantly changed when cultures of fibroblasts from normal kidney tissue were compared to tumor-derived ones." (PMID 21738681, 2011).
cancer (13 papers, 2013 to 2025). A tumor composed of atypical neoplastic, often pleomorphic cells that invade other tissues. "EDA, SEMA3G, ENPP5, EMX2, and OPCML were favorable factors and had low expression levels in ccRCC tissues, whereas PCDHGC3 was a risk factor and highly expressed in cancer tissues." (PMID 36505496, 2022). "Interestingly, emerging evidence suggests that EDA and its receptors can modulate the proliferation, apoptosis, differentiation and migration of cancer cells, and thus may regulate tumorigenesis and cancer progression." (PMID 36012178, 2022). "This review highlights the roles of EDA signaling in different physiological and pathological processes, and discusses the clinical application of Fc-EDA protein in HED and the possible drug development of EDAR inhibitors for cancer treatment." (PMID 36012178, 2022). "They identified several genes (AXIN2, MSX1, PAX9, WNT10A, EDA, BARX, and BRCA1) that may play a role in both hypodontia and cancer development." (PMID 38523193, 2024). "EDA signaling mainly regulates skin appendage development, but emerging evidence suggests that the receptor EDAR, solely in the absence of EDA, may have unexpected functions involved in tumorigenesis and cancer progression." (PMID 36012178, 2022).
infection (5 papers, 2008 to 2020). The state of being infected such as from the introduction of a foreign agent such as serum, vaccine, antigenic substance or organism. "To minimize potential consequences of secondary inflammation and/or infection that might occur as EDA-KO piglets age, we studied piglets within 2–8 days of birth." (PMID 33026343, 2020).
genetic disorder (4 papers, 2022 to 2025). "XLHED is a systemic genetic disease caused by mutation of the EDA gene and deficiency of the signaling protein EDA, which leads to the abnormal development of exocrine glands, hair and teeth." (PMID 36555342, 2022). "The ectoderm-derived epithelial cells express the EDAR, and a hinderance to the EDA-EDAR signaling pathway leads to genetic disorders such as anhidrotic ectodermal dysplasia." (PMID 36555342, 2022).
genodermatosis (1 paper, 2021). "Partial deletion of the EDA gene is the presumed basis for the reported X-chromosomal recessive inherited genodermatosis." (PMID 33801223, 2021).
inflammatory myopathies (1 paper, 2025). "Several tumor necrosis factor (TNF) superfamily genes (TNFSF8, LTB, TNFSF12, TNFSF13B, TNFSF14, TNFSF13, EDA) were upregulated, with LTB and EDA reaching higher levels than in other inflammatory myopathies." (PMID 41441888, 2025).
EDA also shares sentences with these, for which no sentence is quoted: Hypodontia (11 papers); Stroke (11); diabetes (7); fibrosis (3); glomerulosclerosis (3); hypotrichosis (3); renal diseases (3); Type 2 Diabetes (3); Arthritis (2); cardiac interstitial fibrosis (2); cardiovascular diseases (2); colitis (2); glioblastoma (2); glioma (2); hemorrhage (2); Hypertension (2); ischemia (2); kidney damage (2); melanoma (2); myocardial infarction (2); renal fibrosis (2); Alzheimer disease (1); amblyopia (1); aortic stenosis (1); arteriosclerosis (1); asthma (1); atherosclerosis (1); Autoimmunity (1); brain hemorrhage (1); brain ischemia (1).
A further 61 diseases each share a sentence with EDA in 1 paper.